SPARC (secreted protein acidic and cysteine rich)
Diseases named in the same sentence as SPARC in open-access papers (continued):
Sharing a sentence is not in itself a finding about the gene and the disease.
melanoma (continued). "Here, we corroborated that SPARC is a bona fide target of miR-29 in melanoma cell lines that harbor variable miR-29 expression." (PMID 40943659, 2025). "For instance, SPARC promotes melanoma cell invasion by inducing Snail and repressing E-cadherin and contributes to pulmonary fibrosis by regulating ECM turnover." (PMID 41018070, 2025). "Accordingly, we analyzed the Ras-activated pathways potentially involved in basal SPARC expression in melanoma cells." (PMID 40943659, 2025). "This decrease in PRRX1 expression was accompanied by lower SPARC levels across all three subcellular fractions of melanoma cells." (PMID 40943659, 2025). "To assess the relevance of the SPARC-miR-29 axis in melanoma, we explored the relationship between the relative expression of SPARC and the four members of the miR-29 family in clinical melanoma samples from the cutaneous melanoma TCGA-SKCM dataset." (PMID 40943659, 2025). "Collectively, HDAC10 depletion suppresses melanoma cell growth, at least in part, by an increase in SPARC expression." (PMID 38650694, 2024). "Here, we demonstrate that histone deacetylase 10 (HDAC10) is a key regulator of SPARC expression in melanoma cells." (PMID 38650694, 2024). "HDAC10 depletion and resultant SPARC upregulation repress melanoma cell growth primarily by activating AMPK signaling and inducing autophagy." (PMID 38650694, 2024). "In support of this notion, the level of endogenous HDAC10 protein is statistically inversely correlated with endogenous SPARC protein expression in a panel of melanoma cell lines." (PMID 38650694, 2024). "SPARC is highly expressed and has profound implications in several cancer types, including melanoma." (PMID 38650694, 2024). "Further, when exposed to PLX4032, HDAC10-depleted melanoma cells exhibited more pronounced inductions of both SPARC protein and mRNA." (PMID 38650694, 2024). "In melanoma cells the matricellular protein SPARC induced Slug expression and E-cadherin downregulation via PI3-K/Akt signaling." (PMID 38291468, 2024). "Consistent with our results that HDAC10 represses SPARC expression in melanoma cells, in an RNA-seq analysis, SPARC is one of the top upregulated genes upon HDAC10 depletion in H1299 lung cancer cells." (PMID 38650694, 2024). "In contrast, treatment with PLX4032 didn’t significantly change the expression patterns of HDAC10 and SPARC in BRAF WT melanoma cells (SK-MEL-2 and WM3918)." (PMID 38650694, 2024). "In summary, our studies reveal that HDAC10 plays a critical role in the regulation of SPARC expression in the melanoma cells." (PMID 38650694, 2024). "Desmoplastic melanoma (DM) is a unique form of melanoma in which SPARC expression is extremely high." (PMID 37577749, 2023). "Serum levels of SPARC were significantly higher in individuals with melanoma than those in healthy donors." (PMID 37577749, 2023). "SPARC can enhance the permeability of blood vessels, its high expression in acidic media provides motivation, and it is a leader for treating melanoma." (PMID 37577749, 2023). "SPARC stimulates cathepsin B-mediated melanoma invasion through this mechanism using collagen I and α2β1 integrin as mediators." (PMID 37577749, 2023). "Cell migration, adhesion, cytoskeletal features, and cell shape are influenced by the inhibition of SPARC expression in human melanoma cells." (PMID 37577749, 2023). "SPARC can enhance the blocking effect of Pf4 on the phosphorylation of ERK and the metastasis of melanoma cells, and the synergistic effect of SPARC provides the possibility of targeting the secretome of cancer cells for therapeutic development." (PMID 37577749, 2023). "SPARC is believed to promote melanoma cells to acquire mesenchymal traits—traits that can lead to increased metastatic dissemination." (PMID 36230844, 2022). "SPARC is identified as a pro-tumorigenic protein in melanoma, HNSCC and various other cancers, mediating tumor growth, invasion and metastasis via ECM remodeling and EMT induction." (PMID 36232952, 2022).
melanoma (continued). "SPARC expression in melanoma and non-small cell lung cancer cells was reported to induce EMT mediated by AKT phosphorylation." (PMID 33579227, 2021). "Slug knockdown attenuates invasive behavior and blocks SPARC-medicated promotion of cell migration in melanoma." (PMID 35201457, 2021). "Here we show that PF4 and SPARC in the Sec23a-regulated secretome can act cooperatively to inhibit melanoma metastasis." (PMID 34421345, 2021). "Previous studies have shown that SPARC is localized in the tumor stroma and overexpressed in various cancers, such as breast, lung, and melanoma." (PMID 32934754, 2020). "The Secreted protein acidic and rich in cysteine (SPARC) is an oncogene, which is highly expressed in various tumors such as glioma, melanoma, prostate, and gastric carcinoma." (PMID 33628737, 2020). "With regard to SPARC, induction of pFAK formation was observed in glioma and melanoma, while decreased formation of pFAK was reported in ovarian cancer." (PMID 31554208, 2019). "Taken together, SPARC expression appears to correlate with invasion and progression of gliomas and melanomas but in many epithelial cancers, hyper-methylation of the SPARC promoter reduces the amount of SPARC produced by the tumor cells." (PMID 28425924, 2017). "In melanoma, SPARC has been shown to enhance tumorigenesis by inhibiting cytotoxic anti-tumor response." (PMID 29176937, 2017). "High levels of ZEB1 expression undoubtedly promote an invasive phenotype in melanoma, including decreased E‐cadherin and increased expression of Vimentin, SPARC, and MMPs." (PMID 27596438, 2016). "ERK can regulate SMAD function at various levels in TGF-β signaling, but we did not detect any effect of MEK inhibition on SMAD2 steady state or TGF-β-induced nuclear localization, or TGF-β-stimulated transcription of SPARC or VEGF in melanoma cells." (PMID 26977879, 2016). "Those that effect a change in cell-cell cohesiveness (e.g. VIM, SPARC, COL4A1, and the integrins, ITGA4 and ITGAV), and have been shown to be over expressed in human or mouse melanoma samples, are each associated with one or more UV-miRNAs." (PMID 27149382, 2016). "Statistical analysis revealed a significant correlation between enhanced immunoreactivity of ADAM-10 and augmented expression of N-cadherin and SPARC in primary tumor cells and melanoma cells in nodal metastases." (PMID 26266086, 2015). "We found that suppression of SPARC expression in human melanoma cells compromised cell migration, adhesion, cytoskeleton structure, and cell size." (PMID 26248315, 2015). "Taken together, these data show that SPARC modulates differentially melanoma cells capacity to adhere to certain matrices affecting cells’ migration." (PMID 26248315, 2015). "It was unexpected that the modulation by SPARC of the transition to a more aggressive mesenchymal phenotype, and the reversion back, involved a dramatic change in the size of melanoma and pancreatic cancer cells." (PMID 26248315, 2015). "The present data show that SPARC modulates different features of melanoma cell aggressiveness such as cytoskeleton architecture, cell size, and migration." (PMID 26248315, 2015). "SPARC-mediated melanoma cell migratory capacity is SLUG dependent, while the transendothelial migration capacity of melanoma cells is associated with SPARC-driven E- to N-cadherin switching." (PMID 26248315, 2015). "On the other hand, Akt has been shown to mediate SPARC-mediated transition to a mesenchymal phenotype in melanoma cells." (PMID 26248315, 2015). "SPARC can regulate melanoma cell transition to an aggressive mesenchymal phenotype (that implies Rac1-GDP localization at the cytoplasm) by inducing the shift from E- to N-cadherin expression." (PMID 26248315, 2015).
melanoma (continued). "Moreover, we also revealed a significant correlation between enhanced immunoreactivity of ADAM-10 and augmented expression of N-cadherin and SPARC in primary tumor cells and melanoma cells in nodal metastases which may be associated with the potential role of ADAM-10 in the process of EMT." (PMID 26266086, 2015). "SPARC (Secreted Protein Acidic and Rich in Cysteine) is a matricellular protein that promotes this transition in various malignant cell types, including melanoma cells." (PMID 26248315, 2015). "Activation of matrix metalloproteinases (MMPs) by SPARC has been reported in other systems, and we investigate the possibility of such a connection in melanoma using a broad spectrum MMP inhibitor on HTB66 cells treated with MSA." (PMID 23470450, 2013). "The overexpression of SPARC has been documented in several types of solid tumors, such as breast tumors, prostate tumors, melanomas, glioblastomas, esophageal tumors, lung tumors, kidney tumors, bladder tumors and liver tumors." (PMID 23516489, 2013). "SPARC is a key determinant of invasion and metastasis in some tumors, such as gliomas, melanomas and prostate tumors." (PMID 23516489, 2013). "We previously observed an inversed correlation between SPARC and E-cadherin levels in melanocytes and melanoma cells." (PMID 22911700, 2012). "Recently, we showed that autocrine production of SPARC by melanoma cells participates to elevated levels of AKT activation and increased tumor cell survival." (PMID 22911700, 2012). "The positive expression of SPARC mRNA observed in the two VGP melanoma samples confirmed our previous observations that SPARC is induced during the RGP to VGP transition of melanomas." (PMID 22911700, 2012). "Knockdown of SPARC or SLUG with siRNAs in several melanoma cells strongly inhibited melanoma cell migration in Boyden chambers assays, compared with control cells." (PMID 22911700, 2012). "For example, the increased SPARC expression in prostate cancer, bladder cancer, melanoma and non-small cell lung cancer indicated a higher malignancy and invasion of tumors with poor prognosis." (PMID 22321704, 2012). "A similar robust decrease of SLUG expression upon SPARC knockdown was observed in WM9 melanoma cells (right)." (PMID 22911700, 2012). "The overexpression of SPARC also stimulates melanoma cell invasiveness mediated by the phosphorylation of focal adhesion kinase (FAK) and Snail-induced repression of E-cadherin promoter activity." (PMID 22481923, 2012). "To show that SLUG is a downstream target of SPARC in melanoma cells, we knocked down SLUG in SPARC-overexpressing 501mel cells." (PMID 22911700, 2012). "Real-time Q-PCR analysis revealed a positive association between SPARC and SLUG transcripts in freshly isolated melanoma samples tested." (PMID 22911700, 2012). "Several studies from our laboratory and others have shown that inhibition of SPARC in both malignant cells in vitro and tumors in vivo reduces melanoma growth, invasiveness, and induces spontaneous apoptotic cell death and anti-tumor cytotoxic capacity." (PMID 22911700, 2012). "Similar result were also found in melanoma, SPARC can down-regulate E-cadherin and stimulate an invasive melanoma phenotype." (PMID 22879971, 2012). "Suppression of SPARC expression in human melanoma cells reduced their tumorigenic potential in mouse xenograft assays and inhibited migratory and invasive abilities of human melanoma cells in vitro." (PMID 22911700, 2012).
melanoma (continued). "Our study showing that AKT also contributes to SLUG regulation downstream SPARC-induced EMT-like changes in melanomas emphasizes the crucial role of AKT in controlling SNAIL family factors and tumor-associated EMT processes." (PMID 22911700, 2012). "SLUG increase occurred concomitantly with SPARC-mediated downregulation of E-cadherin and P-cadherin, and induction of mesenchymal traits in human melanocytes and melanoma cells." (PMID 22911700, 2012). "So our data indicated that downregulation of SPARC inhibited cell proliferation of gastric cancer cells by apoptosis initiation, which conscience with melanoma and glioma, but contrary to ovarian and pancreatic cancer." (PMID 20525171, 2010). "Overexpression of SPARC has been documented in several types of solid tumors, such as breast, prostate, melanoma and glioblastomas." (PMID 20525171, 2010). "Both CRAds were therapeutically effective on SPARC positive-human melanoma tumors growing in nude mice but exhibited restricted efficacy in the presence of co-administered HMEC-1 or WI-38 cells." (PMID 19337591, 2009). "On the contrary, both CRAds exhibited CPE mainly on SPARC positive-human melanoma cells at relatively moderate viral concentrations of 5×106 to 2.5×107 vp/ml." (PMID 19337591, 2009). "SPARC was reported to be overexpressed in a variety of human malignancies, including melanoma, glioma, meningioma, colorectal, breast, oesophageal, renal cell, prostate, bladder and hepatocellular carcinoma." (PMID 15558074, 2004). "In contrast, immunostaining for SPARC was located mainly in the tumour cells in melanoma cells and oesophageal cancer." (PMID 15558074, 2004). "The suppression of SPARC expression by antisense RNA results in a significant decrease in the tumorigenicity of melanoma cells." (PMID 14562024, 2003). "Our study delves deeper into mechanisms that may converge to regulate SPARC expression in melanoma progression." (PMID 40943659, 2025). "For many years, SPARC has been recognized as a mesenchymal marker in carcinomas and melanomas." (PMID 40943659, 2025). "Collectively, these findings support the hypothesis that endogenous SPARC levels may be controlled, at least in part, by miR-29s in clinical melanoma samples." (PMID 40943659, 2025). "While efforts to decipher SPARC functions in tumors are constantly growing, much less attention is dedicated to investigating the mechanisms that regulate its expression, particularly in melanoma." (PMID 40943659, 2025). "Finally, to assess the impact of miR-29s on endogenous SPARC protein levels, we transduced the melanoma cells with retroviral particles obtained from pMSCV-Blast-miR carrying distinct members of the miR-29 family." (PMID 40943659, 2025). "Accordingly, we hypothesized that activation of the Wnt/β-catenin pathway may be involved in the transactivation of the SPARC promoter in these melanoma cells." (PMID 40943659, 2025). "The expression of the Secreted Protein, Acidic and Rich in Cysteine (SPARC) gene in human melanoma increases during progression and is associated with epithelial-to-mesenchymal transition (EMT), which is a major determinant of metastasis in melanoma patients." (PMID 40943659, 2025). "Nevertheless, it remains unknown whether these EMT-TFs might trigger the overexpression of SPARC mRNA in invasive melanoma cells." (PMID 40943659, 2025). "Since we have recently shown that high expression of PRRX1 in melanoma correlates with invasiveness, we were prompted to explore whether the loss of PRRX1 might impact SPARC expression in invasive melanoma cells." (PMID 40943659, 2025). "Here, we investigated the molecular effectors that regulate SPARC expression in melanoma." (PMID 40943659, 2025). "In light of Kapinas’ work demonstrating the regulation of miR-29 and SPARC during the osteoblast differentiation process, we envision that the phenotype switch in melanoma might induce changes in SPARC expression levels regulated by miR-29 expression." (PMID 40943659, 2025).
melanoma (continued). "To determine whether any of these PRRX1-binding motifs were essential for the SPARC promoter activation, we performed a chromatin immunoprecipitation (ChIP) assay on invasive melanoma cells with high SPARC mRNA and protein expression." (PMID 40943659, 2025). "This led us to explore SPARC and miR-29 expression in the context of melanoma." (PMID 40943659, 2025). "HDAC10 maintained BRAF inhibitor resistance and proliferation of BRAFV600E A375 and WM793 melanoma cells by suppressing the glycoprotein SPARC (secreted protein acidic and rich in cysteine) via regulation of histone H3 acetylation in the SPARC gene regulatory elements together with the HAT p300." (PMID 39935431, 2025). "Furthermore, we demonstrated that SPARC expression correlates with “invasiveness” in melanoma as it forms part of the top 50 genes enriched in the EMT signature of the TCGA-SKCM dataset and independent GEO datasets (GSE 65904, GSE 22155, and GSE 46517)." (PMID 40943659, 2025). "It is known that SPARC and some integrin genes could be positively and reciprocally regulated in carcinoma and melanoma cells." (PMID 40943659, 2025). "Furthermore, we analyzed SPARC expression levels in melanoma cell lines and the effects of MEK/ERK inhibition in vitro." (PMID 40943659, 2025). "Remarkably, while most publications have focused on downstream targets beyond SPARC and the cellular functions of SPARC itself, much less is known about the mechanisms by which this gene is aberrantly expressed in cancers, particularly in melanoma." (PMID 40943659, 2025). "Notably, the basal SPARC expression varies across distinct cancer and/or cell types, e.g. the relative level of SPARC mRNA in melanoma cells (A375 and WM793) is ∼400–1000 times higher than in lung cancer cell lines (H1299 and A549)." (PMID 38650694, 2024). "Notably, the expression dynamics of both HDAC10 and SPARC are influenced by the BRAF activity state in BRAF mutant melanoma cells (A375 and WM793)." (PMID 38650694, 2024). "Furthermore, our work shows that HDAC10 depletion and resultant SPARC upregulation led to repressive melanoma cell growth and increased vulnerability to BRAF inhibition in resistant cells." (PMID 38650694, 2024). "However, in melanoma cells characterized by high SPARC expression, HDAC10 depletion significantly repressed colony and spheroid growth." (PMID 38650694, 2024). "SPARC regulates cell growth and proliferation in certain malignancies, including melanoma." (PMID 38650694, 2024). "SPARC is involved in various aspects of development and growth of melanoma." (PMID 38650694, 2024). "SPARC is one of the indicators that helps identify the progression of melanoma." (PMID 37577749, 2023). "SPARC is found to be strongly expressed in paraffin-embedded samples of melanoma." (PMID 37577749, 2023). "SPARC promotes metastasis and vascular extravasation in melanoma." (PMID 37577749, 2023). "SPARC is bound to become a novel target for the development of melanoma therapies." (PMID 37577749, 2023). "The high expression of SPARC was found by conducting a study on melanoma specimens." (PMID 37577749, 2023). "Interactions between melanoma and other cells are facilitated in a SPARC-dependent form." (PMID 37577749, 2023). "The SPARC gene is a key gene affecting the migration of melanoma." (PMID 37577749, 2023). "The most important finding of the current study is that PF4 transported by SEC23A, may cooperate with another secretory protein SPARC to inhibit melanoma metastasis via inhibition of MEPK/ERK activation." (PMID 34421345, 2021). "Specifically, platelet factor-4(PF4) transported by SEC23A, may cooperate with another secreted protein acidic and rich in cysteine (SPARC) to inhibit melanoma metastasis via inhibition of MEPK/ERK activation." (PMID 34421345, 2021). "However, in melanoma, SPARC inhibition through stable transfection of short hairpin RNA targeting the SPARC transcript increased neutrophil recruitment, inhibiting tumour growth." (PMID 33187209, 2020).